SIX1 (SIX homeobox 1)
Diseases named in the same sentence as SIX1 in open-access papers (continued):
Sharing a sentence is not in itself a finding about the gene and the disease.
tumor (continued). "The results above demonstrate that in the context of ES, the impact of SIX1 expression on metastasis is opposite to that in most other described tumor types." (PMID 37468459, 2023). "Here, the authors suggest that SIX1, which enhances metastasis in most tumour types, suppresses ES metastasis by co-regulating EWS/FLI1 target genes." (PMID 37468459, 2023). "Tumor growth was decreased in an immune-dependent way, and the anti-tumor immunity was strengthened in the tumor microenvironment with the silence of SIX1." (PMID 36750914, 2023). "We performed immunofluorescence on tumor samples embedded in paraffin to investigate the impact of SIX1 on the expression of stem cell-related markers in tumor tissues." (PMID 38031089, 2023). "In numerous cancer contexts, SIX1 positively regulates proliferation, tumor-initiating-cell characteristics, and migration and invasion, resulting in tumor progression and metastasis." (PMID 37468459, 2023). "This anti-metastatic function for SIX1 is in contrast to previous reports demonstrating pro-metastatic functions for SIX1 in other tumor types, underscoring the importance of genetic background when studying developmental regulators in cancer." (PMID 37468459, 2023). "SIX1 expression in tumor tissues was significantly higher than normal tissues in GSE17025, GSE36389, GSE11580, GSE11580 and the current study datasets." (PMID 37723477, 2023). "An increasing number of studies have found that SIX1 plays an important role in tumor glycolysis, thereby promoting tumor progression." (PMID 36937004, 2023). "As we begin to assess the anti-cancer utility of SIX1 complex-targeted therapies, currently under development by our and other laboratories, it is vital to understand tumor-specific functions of SIX1 in order to guide safe and effective use of such therapies." (PMID 37468459, 2023). "Loss of SIX1 restores the MYOD1/MYF4 gene regulatory network, induces tumor cell differentiation, and inhibits in vivo tumor growth." (PMID 37345159, 2023). "The TF SIX1 maintains the cells in an undifferentiated state by reprogramming MYOD1 to occupy loci that drive tumor growth instead of muscle differentiation." (PMID 37345159, 2023). "Future studies will be needed to test SIX1-dependent tumor stemness capacity in vivo models of HCC, and also additional studies will be required to assess the association between CD90 and SIX1 expression profiles in HCC cell colonies." (PMID 37427884, 2023). "Overexpression of Six1 has been shown to promote tumor growth and metastasis in the breast cancer via both increasing TGF-β signaling and converting it from suppressive to supportive mode for tumor growth." (PMID 37305018, 2022). "To further investigate the potential oncogenic effects of SIX1, we generated the subcutaneous tumor by injecting A549/Lv-Ctrl cells and A549/Lv-SIX1 cells (5×106 cells/mouse) in BALB/c nude mice." (PMID 35069900, 2022). "We identify SNS-032, a recently reported antagonist of CDK2/7/9 that exerts anti-tumor activities in multiple cancers 21-24, as an outstanding inducer of SIX1 degradation by downregulating expression of USP1 and triggering K48-linked ubiquitination of SIX1." (PMID 35414775, 2022). "Six1 and Six2 are homologous typing transcription regulators, which can affect and regulate the downstream gene expression related to tumor cell migration and proliferation through a variety of signaling pathways." (PMID 36062065, 2022). "Our findings demonstrated that circ_0017639 promoted DDP resistance and tumor progression via sequestering miR-1296-5p and subsequent elevating SIX1 expression." (PMID 35287543, 2022). "SIX1 has been identified as a therapeutic target for HCC owing to its involvement in tumor onset and progression." (PMID 35193488, 2022). "SIX1 is upregulated in human tumor tissues, and its expression levels are negatively correlated with immune cell infiltration in the tumor microenvironment and the overall survival rates of cancer patients." (PMID 35193488, 2022).
tumor (continued). "The results showed that overexpression of SIX1 significantly facilitated tumor growth in vivo (p< 0.05)." (PMID 35069900, 2022). "For instance, transcription factor SIX1 increased the expression of glycolytic genes and promoted tumor growth." (PMID 35869499, 2022). "Data confirmed that SIX1 was overexpressed in the Lv-SIX1 tumor tissues compared with the control group, mainly located at the nucleus." (PMID 35069900, 2022). "In conclusion, we demonstrated that SIX1 was markedly upregulated in tumor tissues than the corresponding adjacent normal tissues in NSCLC." (PMID 35069900, 2022). "In conclusion, circ_0017639 conferred DDP resistance and promoted tumor growth via elevating SIX1 expression through sequestering miR-1296-5p in NSCLC, providing a new mechanism for understanding the chemoresistance and progression of NSCLC." (PMID 35287543, 2022). "TCGA dataset showed that SIX1 expression levels in normal tissues were higher than in tumor tissues (p = 0.0018)." (PMID 35458126, 2022). "Accumulating evidence has suggested that SIX1 was involved in tumor initiation and progression by regulating multiple activities of cancer cells." (PMID 35069900, 2022). "Overall, our studies identified a novel pathway by which abnormal expression of SIX1 in cancer cells promotes tumor growth through upregulation of TGFBR2 and collagen to suppress immune cell infiltration and activation in the TME." (PMID 34782761, 2021). "The results revealed that the mRNA expression levels of DLX4, FBN1, HIC1, HOXB9, ONECUT2, and SIX1 were significantly different between tumor samples and normal tissues, which were consistent with the results from TCGA." (PMID 35095892, 2021). "Deletion of Six1 in cancer cells significantly reduced tumor growth in an immune-dependent manner with enhanced antitumor immunity in the TME." (PMID 34782761, 2021). "Here, we discovered an unexpected role for the transcription factor SIX1 in regulating the tumor immune microenvironment." (PMID 34782761, 2021). "As SIX1 is rarely expressed in adult tissues, our studies suggested the possibility that aberrant expression of the Six1 gene in tumor tissue contributed to tumor growth through collagen accumulation in the TME, leading to suppression of antitumor immunity." (PMID 34782761, 2021). "Previous studies have shown that SIX1 promotes tumor lymphangiogenesis, angiogenesis, growth, and metastasis [22, 47,]." (PMID 34782761, 2021). "Based on analyses of patient datasets, we found that SIX1 was upregulated in human tumor tissues and that its expression levels were negatively correlated with immune cell infiltration in the TME and the overall survival rates of cancer patients." (PMID 34782761, 2021). "The results showed that both WT cells and Six1−/− cells developed into tumors in all transplanted nude mice, suggesting that Six1 affected tumor growth in an immune-dependent manner." (PMID 34782761, 2021). "Deletion of Six1 in cancer cells strongly inhibited tumor growth in C57BL/6N mice by inducing an adaptive immune response." (PMID 34782761, 2021). "What is more, SIX1 can also upregulate the well-known oncogene c-Myc and contribute to tumor growth in human cancer cells." (PMID 32399910, 2021). "Overall, our studies, combined with the literature, suggest a potential working model of SIX1-mediated tumor growth." (PMID 34782761, 2021). "Lactate production analysis of the tumor masses further validated that miR-489 significantly repressed the lactate production via SIX1." (PMID 32258386, 2020). "Oncofetal protein sine oculis-related homeobox 1 (SIX1) is a transcription factor that plays a key role in the proliferation and development of tumor cells and is a development EMT regulator." (PMID 33343628, 2020). "Consistent with in vitro results, Western blotting and immunohistochemistry revealed enhanced expression of Six1 in anti‐miR‐155‐3p tumours." (PMID 32220051, 2020).
tumor (continued). "SIX1 has been found to be overexpressed in various kinds of caner 15-17 and is known to be involved in the tumor progression in both proliferation and metastasis 18-21." (PMID 32863962, 2020). "In EC, SIX1 also plays an important role, and as a disease biomarker, its overexpression can promote the growth of tumor cells through ERK- and AKT-mediated pathways." (PMID 33343628, 2020). "Numerous conclusive evidence had indicated that overexpression of SIX‐1 in advanced malignancies is a key regulator for tumour metastases." (PMID 32227618, 2020). "Here, we found that SIX1 overexpression facilitated glucose uptake into tumor cells and increased ATP production in HNSCC cells, suggesting that SIX1 was a positive regulator of glucose metabolism in HNSCC." (PMID 32201523, 2020). "In several cancers, the Six1 signalling pathway has been found to be aberrant and also relates to the formation of tumours." (PMID 32220051, 2020). "Our findings illustrate a novel feedback loop of SIX1 and O-GlcNAcylation and show that O-GlcNAcylation of SIX1 is an important way to coordinate glucose metabolism and tumor progression." (PMID 32863962, 2020). "The results of SIX1 GO-terms enrichment analysis revealed that SIX1 was negatively related to anti-tumor immune response and T cell activity but positively correlated to embryonic development." (PMID 32550045, 2020). "As determined by IHC staining, SIX‐1 expression was significantly up‐regulated in BC tissues compared with paired non‐tumour breast tissues." (PMID 32227618, 2020). "We show that SIX1 can facilitate tumor growth and further increase HBP gene expression, glucose uptake, and the level of O-GlcNAcylation." (PMID 32863962, 2020). "Cell Counting Kit 8 (CCK8), colony formation and mouse tumor model assays were used to establish the role of SIX1 and O-GlcNAcylation in HCC processes." (PMID 32863962, 2020). "Considering the role of senescence as a tumor protective barrier and the link of SIX1 to senescence in fibroblasts, we set here to investigate the role of SIX1 in fibroblast transformation and tumorigenesis, in connection with cellular senescence." (PMID 30723235, 2019). "MTT assays showed the tumor cell growth rate significantly increased after ectopic expression of SIX1 and decreased after silencing the endogenous SIX1 expression, which were in accord with the findings from cell growth curve." (PMID 31921695, 2019). "Recent results show that SIX1 also acts as a repressor of cell senescence, an antiproliferative response with a key role in tumor suppression, among other physiological and pathological settings." (PMID 30723235, 2019). "As a critical member of the Retinal Determination Gene Network (RDGN), SIX1 has been regarded as a tumor promoter in various types of cancer." (PMID 31921695, 2019). "p16Ink4a expression was already dramatically reduced in immortalized and Ras-transformed SIX1-expressing cells before tumor formation and this pattern was retained in tumor-derived cell lines." (PMID 30723235, 2019). "We also performed IHC on the tumour tissue sections in mouse xenografts to evaluate the levels of SIX1 and other downstream factors." (PMID 29435409, 2018). "As expected, tumours from the Panc1shctrl group showed a higher expression of Six1 than tumours from the Panc1shSix1 group." (PMID 28388884, 2017). "In our experiment, control tumours displayed a significantly stronger expression CD24+/CD44+ cells than tumours with down-regulation of Six1." (PMID 28388884, 2017). "In tumour biology, however, Six1 exerts pro-tumourigenic functions by regulating EMT-related mechanisms." (PMID 28388884, 2017). "TGF-β signaling can also be enhanced by the sine oculis homeobox homolog 1 (SIX-1) expressed in tumor cells." (PMID 28036019, 2016). "SIX1 also active cyclin A1 expression to promote proliferation; furthermore, transform mammary epithelial cells and promote aggressive tumor formation and peritumoral lymphovascular invasion." (PMID 27203207, 2016).
tumor (continued). "The clinical relevance of this interaction is underscored by the finding that Six1 expression strongly correlates with decreased RPL26 across numerous tumour types." (PMID 26687066, 2015). "More importantly, the misexpression of Six1 in cancer can induce developmental programs out of context, contributing to tumor onset and progression." (PMID 23527134, 2013). "We further show that endogenous Six1 can enhance tumor initiation in an immunocompetent mouse model, and in this context, where ERK signaling is regulated by Six1, inhibition of ERK signalling, dramatically decreases metastasis." (PMID 22765220, 2012). "It should be noted that we have found that while Six1 enhances TICs as measured by in vivo tumor initiation in all contexts examined, we have found that changes in flow cytometric TIC markers are not always consistent with in vivo TIC results." (PMID 22765220, 2012). "In this paper we show that Six1 enhances a tumor initiating phenotype and that its expression is specifically associated with worsened prognosis in luminal B tumors." (PMID 22765220, 2012). "Administration of AZD6244 dramatically inhibits tumor formation efficiency and metastasis in cells that express high levels of Six1 ectopically or endogenously." (PMID 22765220, 2012). "Overexpression of SIX1 in the mouse mammary gland promoted an expansion of stem/progenitor cells and subsequent tumor development." (PMID 21952072, 2011). "Increased Six1 protein expression in HCC patients was significantly correlated with pathologic tumour-node-metastasis (pTNM) stage (P=0.002), venous infiltration (P=0.004) and poor overall survival (P=0.0423)." (PMID 17008870, 2006). "Agreed with other studies, we found that overexpression of Six1 frequently occurred in tumour tissues of human HCC patients in terms of about 85% in mRNA level and 60% in protein level." (PMID 17008870, 2006). "miR-30b can inhibit the PI3K/AKT (phosphoinositide 3-kinase/protein kinase B) signaling pathway through the regulation of EGFR, AKT, Derlin-1, GNA13), SIX1, and other target genes, thus inhibiting the epithelial–mesenchymal transition process of tumor cells and promoting apoptosis." (PMID 40075907, 2025). "Moreover, RNA sequencing (RNA-seq) using tumor tissues from the Alb-Cre;S225Kfl/fl and S225Kfl/fl groups showed that SIX1 S225K knock-in regulated expression of many genes, including the glycolytic genes LDHA, ENO1, and PKM." (PMID 39617783, 2024). "In summary, we found that LINC02936, the TF SIX1, and its target gene CP are highly expressed and related to poorer outcomes in patients with EC, and act as an oncogenic role in regulating ferroptosis and tumor progression." (PMID 38385087, 2024). "SIX1 was found to accelerate tumor cell growth in vitro and in vivo." (PMID 39199296, 2024). "Moreover, T276A SIX1 decreased O-GlcNAcylation levels, consequently reducing SIX1-mediated tumor-promoting capabilities." (PMID 39199296, 2024). "SIX1 also plays an important role in tumor invasion and metastasis." (PMID 36750914, 2023). "SIX1 in cooperation with EYA2 promoted tumor cell metastasis by inducing TGF-β signaling and EMT." (PMID 36750914, 2023). "SIX1 promoted stem or progenitor cell phenotype and induced EMT in tumor cells, indicating that SIX1 knockdown may be a method of inhibiting tumor growth and delaying tumor progression." (PMID 36750914, 2023). "Because SIX1-mediated inhibition of metastasis contrasts with pro-metastatic functions observed in other tumor contexts, we asked whether this effect is generalizable across multiple models of ES." (PMID 37468459, 2023).
tumor (continued). "Modulation of tumor differentiation may be attributed to HNF4α-mediated inhibition of mesodermal lineage markers SIX1 and SIX4 that are activated in the basal molecular subtype of PDAC21." (PMID 37974020, 2023). "Moreover, our in vitro and in vivo experiments confirmed that SIX1 can promote the increase in the proportion of stem cells and tumor progression." (PMID 38031089, 2023). "To verify whether four EMT-related genes (SIX1, SIRT2, CDKN2A and PGR) are associated with tumor metastasis, we performed transwell migration assays, transwell invasion assays and wound healing assays to investigate their relationship." (PMID 37723477, 2023). "Overexpression of SIX1 has been noted in various tumours and it has been suggested that upregulation may inhibit apoptosis." (PMID 36834703, 2023). "Furthermore, the SIX1-Q177R tumor that was used to generate the ChIP-seq data was homozygous for the mutation, while the overwhelming majority of SIX1/2-Q177R tumors in the microarray and RNA-seq datasets harbored heterozygous mutations." (PMID 37815464, 2023). "Additionally, recent studies have shown that SIX1 directly increases the transcription of glycolysis genes and enhances the glycolysis of cancer cells to promote tumor growth." (PMID 35069900, 2022). "In vivo experiment was conducted to further validate the tumor-promoting effects of SIX1." (PMID 35069900, 2022). "Additionally, SIX1 levels were increased in BC patient tumor samples compared to normal samples, as evidenced by the analysis of The Cancer Genome Atlas database using GEPIA." (PMID 34711117, 2021). "Thus, our study uncovers a crucial role for SIX1 in modulating tumor immunogenicity and provides proof-of-concept evidence for targeting SIX1 in cancer immunotherapy." (PMID 34782761, 2021). "The tumor-suppressing role of EYA2 in HCC is unexpected because the previous experiments indicated a positive role of EYA2 in regulation of pro-metastatic characteristics of breast cells through the TGF-β pathway by working in concert with SIX1 protein." (PMID 34044846, 2021). "Previous work has elucidated the roles of SIX1 in tumor metabolism, growth, and poor prognoses." (PMID 34782761, 2021). "Indeed, RNA-seq analysis of tumor tissues showed that antitumor immune response genes were expressed at higher levels in tumors developed from Six1−/− cells than those developed from Six1+/+ cancer cells." (PMID 34782761, 2021). "Moreover, SARC and COAD tumor tissues were divided into two groups according to the expression level of SIX1." (PMID 34782761, 2021). "Moreover, an in vivo test also confirmed that overall tumor weight and volume were also increased following SIX1 upregulation." (PMID 32863962, 2020). "EYA2 is required for the ability of SIX1 in mediating tumor progression." (PMID 32258386, 2020). "SIX1 has been shown to promote tumor cell proliferation, migration, and invasion." (PMID 32258386, 2020). "This study indicates that SIX1/O-GlcNAcylation might be a significant pathway for tumor proliferation and a promising therapeutic target for treating HCC." (PMID 32863962, 2020). "SIX1 makes a notable contribution to tumor growth and metastasis." (PMID 33293473, 2020). "To clarify whether progression of BC correlated with dysregulation of SIX‐1, we first detected the expression of SIX‐1 on a tissue chip by immunohistochemistry (IHC), which contains 45 pairs of BC tissues and paired non‐tumour breast tissues." (PMID 32227618, 2020). "SIX1 mediates tumor initiation and metastasis by regulating various activities of cancer cells, including cell differentiation 18, proliferation 19, 20, the epithelial-mesenchymal transition (EMT) process 10, 21, responsiveness to apoptotic stimuli 12 and genome stability." (PMID 32201523, 2020). "Furthermore, rescue experiments indicated that enforced SIX1 expression abolished the tumor suppressive roles of miR-140-5p and its effects on growth and apoptosis of CML by directly targeting SIX1." (PMID 30962263, 2019).